XPO7 (exportin 7)
Description:
Mediates the nuclear export of proteins (cargos) with broad substrate specificity. In the nucleus binds cooperatively to its cargo and to the GTPase Ran in its active GTP-bound form. Docking of this trimeric complex to the nuclear pore complex (NPC) is mediated through binding to nucleoporins. Upon transit of a nuclear export complex into the cytoplasm, disassembling of the complex and hydrolysis of Ran-GTP to Ran-GDP (induced by RANBP1 and RANGAP1, respectively) cause release of the cargo from the export receptor. XPO7 then return to the nuclear compartment and mediate another round of transport. The directionality of nuclear export is thought to be conferred by an asymmetric distribution of the GTP- and GDP-bound forms of Ran between the cytoplasm and nucleus.
Synonyms: Exp7; KIAA0745; RANBP16
Tractability: PROTAC: ubiquitination databases record sites on it; its protein half-life has been measured.
Gene: Protein-coding gene on chromosome 8 (21,919,641 to 22,006,585, forward strand). Ensembl gene ENSG00000130227.
Subcellular location: Cytoplasm; Nucleus
Gene Ontology:
Molecular function: nuclear export signal receptor activity; protein binding; small GTPase binding
Biological process: protein export from nucleus; intracellular protein transport; nuclear transport; nucleocytoplasmic transport
Cellular component: cytoplasm; nuclear pore; nucleus
Genetic constraint (gnomAD): Loss-of-function variants: 17 observed, 136.62 expected, observed/expected ratio (o/e) 0.12, 90% interval 0.084 to 0.19. The upper end of that interval is the gene's LOEUF score, 0.19, which puts it in group 1 of 6, group 1 being the genes least tolerant of losing a copy. Missense variants: 776 observed, 1,321.4 expected, observed/expected ratio (o/e) 0.59, 90% interval 0.55 to 0.62. Synonymous variants: 556 observed, 503.71 expected, observed/expected ratio (o/e) 1.1, 90% interval 1.03 to 1.18.
Homologues: Orthologues: dog XPO7 (99% identical), guinea pig XPO7 (99% identical), mouse Xpo7 (99% identical), rat Xpo7 (99% identical), chimpanzee XPO7 (99% identical), pig XPO7 (99% identical), rabbit XPO7 (99% identical), macaque XPO7 (98% identical), zebrafish xpo7 (96% identical), tropical clawed frog xpo7 (93% identical), Drosophila melanogaster Ranbp16 (59% identical), Caenorhabditis elegans C35A5.8 (42% identical). Paralogues in human: RANBP17 (67% identical), XPO4 (21% identical).
Diseases named in the same sentence as XPO7 in open-access papers:
XPO7 is named in the same sentence as 28 diseases in open-access papers, as found by Europe PMC text mining. Sharing a sentence is not in itself a finding about the gene and the disease. The quoted sentences say what the papers report.
ovarian carcinoma (3 papers, 2014 to 2021). A malignant neoplasm originating from the surface ovarian epithelium. "However, XPO7 knockdown has been implicated as a probable therapeutic target in conjunction with XPO1 knockdown in various neurodegenerative diseases such as dementia, amyotrophic lateral sclerosis (AML) and ovarian cancer and its overexpression in cancer results in poor outcomes." (PMID 31569391, 2019). "However, multivariate analyses demonstrate a higher risk for patients expressing either RAN or TPX2 than for those expressing XPO7, suggesting a more significant contribution of RAN’s mitotic function to ovarian cancer progression than its nucleo-cytoplasmic function." (PMID 24625450, 2014).
schizophrenia (2 papers, 2023 to 2025). A major psychotic disorder characterized by abnormalities in the perception or expression of reality. "Recent genetic studies by the Schizophrenia Exome Sequencing Meta-Analysis (SCHEMA) consortium have identified that protein-truncating variants of exportin 7 (XPO7) can increase the risk of schizophrenia (odds ratio, 28.1)." (PMID 39774335, 2025). "Even though rare variants like XPO7 insufficiency may display specific pathological mechanisms, they are also likely to involve pathogenic pathways relevant to common schizophrenia variants." (PMID 39774335, 2025). "Moreover, the clinical information for patients with schizophrenia with XPO7 variants, including detailed case reports, is important for further understanding the pathogenesis of XPO7 deficiency." (PMID 39774335, 2025). "XPO7 haploinsufficiency increases the risk of schizophrenia." (PMID 39774335, 2025). "The involvement of Gria3 in Xpo7-mediated pathological pathways is significant in its impact on schizophrenia-related pathology." (PMID 39774335, 2025). "Therefore, it is essential to investigate whether the candidate pathologies identified in Xpo7 insufficiency are also involved in other rare but high-odds haploinsufficiency variants, as such a common pathogenic pathway would be shared with a broader spectrum of schizophrenia patients." (PMID 39774335, 2025). "In addition, Xpo7+/− mice showed deficits in pre-pulse inhibition at both 3 and 6 months of age, which is a recognized endophenotype of schizophrenia." (PMID 39774335, 2025). "Also, a large-scale exome sequencing study identified single genes whose rare mutations substantially increase the risk for schizophrenia, of which six genes (SETD1A, CUL1, XPO7, GRIA3, GRIN2A, and RB1CC1) showed odds ratios larger than ten." (PMID 36878965, 2023). "In addition, it is crucial to consider the broader implications for schizophrenia, which are caused by a complex interaction of common genetic variants rather than XPO7 mutations." (PMID 39774335, 2025). "This understanding may provide insights into preventing the onset and progression of the disease in a broader range of patients with schizophrenia, not just those with XPO7 haploinsufficiency." (PMID 39774335, 2025).
alcohol dependence (1 paper, 2020). Physical and psychological dependence on alcohol. "XPO7 mediates the nuclear export of proteins with broad substrate specificity and was identified as one of the significant genes in a genome-wide association study on alcohol dependence." (PMID 32245436, 2020). "However, its mechanism in alcohol dependence or mood disorders is unclear because of the lack of current literature linking XPO7 function with psychiatric manifestations." (PMID 32245436, 2020).
Anxiety (1 paper, 2025). Intense feelings of nervousness, tension, or panic often arise in response to interpersonal stresses. "Xpo7+/− mice exhibited normal locomotor activity and anxiety in the open field and elevated plus maze tests (Fig. EV4B,C)." (PMID 39774335, 2025).
bipolar disorder (1 paper, 2020). A disorder of the brain that causes unusual shifts in mood, energy, activity levels and the ability to carry out day-to-day tasks. "Ras-related protein Rab-7a, Rho-associated protein kinase 2, and Exportin-7 were identified as potential peripheral protein candidates to distinguish major depressive disorder and bipolar disorder." (PMID 32245436, 2020).
cognitive deficits (1 paper, 2025). "The behavioral analysis showed that Xpo7+/− mice displayed cognitive deficits and impaired pre-pulse inhibition from 3 to 6 months of age." (PMID 39774335, 2025). "The onset of cognitive deficits was defined at 3 months of age, as Xpo7+/− mice showed normal cognitive function at 2 months (Fig. EV4A)." (PMID 39774335, 2025).
colon adenocarcinoma (1 paper, 2021). "In particular, deletions of XPO7 occurred in a significant percentage of samples obtained from different tumor types, including prostate adenocarcinomas (PRAD), colon adenocarcinomas (COAD), or liver hepatocellular carcinomas (LIHC), among others." (PMID 33602872, 2021).
endometrial cancer (1 paper, 2016). Primary or metastatic malignant neoplasm involving the endometrium (mucous membrane that lines the endometrial cavity). "In addition, 1 somatic alteration (chr8:21827087) on XPO7 (Ran GTPase binding protein) was identified to be expression-associated in endometrial cancer, which was correlated with expression levels of 32 genes." (PMID 26716509, 2016).
hepatocellular carcinoma (1 paper, 2021). A malignant tumor that arises from hepatocytes. "Since hepatocellular carcinomas are one of the tumor types in which we observed significant deletions of XPO7, we took advantage of a liver model of OIS." (PMID 33602872, 2021).
liver cancer (1 paper, 2021). An epithelial or non-epithelial malignant neoplasm that arises from the liver. "We provided further evidence for the dual role of XPO7 in regulating senescence and tumor suppression using a mouse model of OIS and tumor initiation in liver cancer." (PMID 33602872, 2021). "Moreover, depletion of XPO7 alleviated OIS and increased tumor formation in a mouse model of liver cancer." (PMID 33602872, 2021).
serous carcinoma (1 paper, 2014). "Based on Kaplan-Meier analyses, RAN, cytoplasmic XPO7 and TPX2 were significantly associated with poor overall patient survival, and RAN and TPX2 were associated with lower disease free survival in patients with high-grade serous carcinoma." (PMID 24625450, 2014).
tumor (5 papers, 2014 to 2024). "Given that XPO7 is often deleted or mutated in cancer, our results suggest that XPO7 is a novel tumor suppressor regulating senescence." (PMID 33602872, 2021). "It will be interesting in the future to determine which of XPO7 cargoes are mostly associated with tumor malignancy and clinical progression." (PMID 24625450, 2014). "In female mice, the transcription level of Xpo7 was significantly downregulated, and the gene is a new type of tumor suppressor that controls aging and tumor occurrence by regulating the expression of P21CIP1 in a previous study." (PMID 40303139, 2024). "In summary, we identified the nuclear exportin XPO7 as a novel regulator of senescence and tumor suppression." (PMID 33602872, 2021). "Our results suggest that XPO7 is a novel tumor suppressor that regulates p21CIP1 expression to control senescence and tumorigenesis." (PMID 33602872, 2021). "Data derived from the TCGA unveiled different cancer types (including tumors of the liver, colon, or prostate) in which deletions of XPO7 are significant." (PMID 33602872, 2021). "Altogether, these results indicate that XPO7 is a novel tumor suppressor gene that functions by regulating senescence." (PMID 33602872, 2021). "Some of these genes (CHMP7, XPO7, KIAA1967) are reported to be tumor suppressor genes." (PMID 38896472, 2024). "Reinforcing the hypothesis that XPO7 could be a novel tumor suppressor, PRAD patients with heterozygous or homozygous deletion of XPO7 had a significantly worse progression-free survival than their wt counterparts." (PMID 33602872, 2021).
cancer (4 papers, 2019 to 2025). A tumor composed of atypical neoplastic, often pleomorphic cells that invade other tissues. "Moreover, low expression of XPO7 or XPO7 loss correlated with worse outcome in cancers of the prostate or the colon." (PMID 33602872, 2021). "We found that the majority of XPO were significantly upregulated in tumors, while XPO4 and XPO7 were downregulated in some cancer types." (PMID 39882192, 2025). "Given the ability of XPO7 to control senescence, we searched for evidence of a role of XPO7 in cancer." (PMID 33602872, 2021). "Our work provides a basis to elucidate the role of XPO7 in cancer." (PMID 33602872, 2021). "Deletion of XPO7 correlates with poorer overall survival in several cancer types." (PMID 33602872, 2021).
infection (2 papers, 2019 to 2024). The state of being infected such as from the introduction of a foreign agent such as serum, vaccine, antigenic substance or organism. "In female mice, there were 430 DEGs in the infection group (FT) compared with the control group (FC), 195 genes with upregulated expression, such as Ifitm1, Wfdc21, Wfdc17, RARα, and Mgam (P < 0.001), and 235 genes with downregulated expression, such as Xpo7 and Hmbs (P < 0.001)." (PMID 40303139, 2024).
XPO7 also shares sentences with these, for which no sentence is quoted: acute myeloid leukemia (1 paper); amyotrophic lateral sclerosis (1); atrial fibrillation (1); breast carcinoma (1); colon tumors (1); coronary artery disease (1); dementia (1); latent infection (1); lung carcinoma (1); major depressive disorder (1); mood disorder (1); neurodegenerative disease (1); prostate adenocarcinoma (1); serous ovarian carcinomas (1).